ELAPOR2 (endosome-lysosome associated apoptosis and autophagy regulator family member 2)
Description:
Functions as a regulator of the BMP signaling pathway and may be involved in epidermal differentiation.
Synonyms: EIG121L; KIAA1324L; FLJ31340
Tractability: Antibody: UniProt places it where antibodies can reach, with medium confidence; UniProt predicts a signal peptide or a membrane-spanning region; its Gene Ontology location is reachable by antibodies, with medium confidence.
Gene: Protein-coding gene on chromosome 7 (86,876,906 to 87,059,693, reverse strand). Ensembl gene ENSG00000164659.
Subcellular location: Cell membrane
Subcellular location (Human Protein Atlas): Endoplasmic reticulum
Gene Ontology:
Molecular function: protein binding; BMP receptor binding
Biological process: negative regulation of nervous system development; positive regulation of BMP signaling pathway; positive regulation of epidermis development
Cellular component: membrane; plasma membrane
Genetic constraint (gnomAD): Loss-of-function variants: 63 observed, 82.78 expected, observed/expected ratio (o/e) 0.76, 90% interval 0.62 to 0.94. The upper end of that interval is the gene's LOEUF score, 0.94, which puts it in group 3 of 6, group 1 being the genes least tolerant of losing a copy. Missense variants: 878 observed, 965.5 expected, observed/expected ratio (o/e) 0.91, 90% interval 0.86 to 0.96. Synonymous variants: 349 observed, 348.05 expected, observed/expected ratio (o/e) 1, 90% interval 0.92 to 1.1.
Homologues: Orthologues: chimpanzee ELAPOR2 (99% identical), macaque ELAPOR2 (99% identical), pig ELAPOR2 (95% identical), rabbit ELAPOR2 (95% identical), rat Elapor2 (94% identical), mouse Elapor2 (93% identical), guinea pig ELAPOR2 (88% identical), tropical clawed frog elapor2 (71% identical), zebrafish elapor2b (63% identical), zebrafish elapor2a (62% identical), zebrafish si:dkey-5i3.1 (6% identical). Paralogues in human: ELAPOR1 (53% identical).
Diseases named in the same sentence as ELAPOR2 in open-access papers:
ELAPOR2 is named in the same sentence as 5 diseases in open-access papers, as found by Europe PMC text mining. Sharing a sentence is not in itself a finding about the gene and the disease.
ELAPOR2 shares sentences with these, for which no sentence is quoted: breast carcinoma (1 paper); inflammation (1); mood disorder (1); neurodegenerative disease (1); pancreatic cancer (1).